IL6 (interleukin 6)
Diseases named in the same sentence as IL6 in open-access papers (continued):
Sharing a sentence is not in itself a finding about the gene and the disease.
Arthritis (continued). "In addition, IL-6-deficient mice did not develop arthritis symptoms or joint destructions." (PMID 30587175, 2018). "Arthritis score, tumor necrosis factor (TNF)-α, interleukin (IL)-6, and C reactive protein (CRP) levels in the serum were measured by enzyme-linked immunosorbent assay (ELISA)." (PMID 27900440, 2018). "Psoralen was reported to treat arthritis by regulating the balance of Th1/Th2 cells and inhibiting the expression of TNF-α, IL-6, and IL-1β." (PMID 29922598, 2018). "The arthritis index and serum levels of TNF-α and IL-6 were decreased as compared to the control group." (PMID 29681976, 2018). "osteoarthritis is the most common form of arthritis and involves multiple proinflammatory cytokines, including IL-1β, TNF, and IL-6." (PMID 30542285, 2018). "Morphology, X-ray images of the joints, pathological images, arthritis index, and cytokine (TNF-α and IL-6) levels were evaluated." (PMID 29681976, 2018). "Similarly, the production of IL-6 together with TGF-β has been shown when “activated” apoptotic cells or apoptotic cells containing high amounts of demethylated DNA have been infused in mBSA arthritis model instead of “resting” apoptotic cells rather containing methylated DNA." (PMID 29062314, 2017). "Herein, we found that DXM treatment attenuated arthritis severity and proinflammatory cytokine expression levels, including TNF-α, IL-6, and IL-17A, in paw tissues of CIA mice." (PMID 28900117, 2017). "Therefore, the purpose of this study was to determine whether IL-6/IL-21 combinatorial pathway blockade has additional inhibitory effects on Th17 differentiation, and more effectively reduces development of T cell-dependent experimental arthritis." (PMID 28158305, 2017). "The release of IL-6 and CXCL1/KC to the synovial fluid increased 7 days after induction of arthritis, albeit CXCL1/KC concentration was just slightly above the detection limit." (PMID 28587618, 2017). "After injection with complete Freund's adjuvant, body weight, arthritis score, and the serum levels of TNF-α, IL-1β, IL-6, myeloperoxidase (MPO), malondialdehyde (MDA), superoxide dismutase (SOD), and glutathione peroxidase (GSH-PX) were assessed." (PMID 28491105, 2017). "Since the immune function of CFA, the serum levels of IFN-γ, IL-6, IL-17A and TNF-α in PDCD5 tg mice and their arthritis control were significantly increased, however the production of pro-inflammatory cytokines in PDCD5 tg mice were relatively inhibited." (PMID 29228993, 2017). "In particular, palmitic acid upregulated IL-6 in human chondrocytes and fibroblast-like synovial cells via TLR4 signaling in an arthritis model." (PMID 29097726, 2017). "AIA in the rat and G6PI-induced arthritis in the mouse are both T cell-dependent arthritis models that require TNF and IL-6 for arthritis development." (PMID 27340371, 2016). "Transfer of IL-17-deficient donor bone marrow into CIA DBA/1J mice inhibits development and severity of clinical arthritis, due to reduction in the secretion of the pro-inflammatory cytokines TNF-α, IL-1β and IL-6." (PMID 26634933, 2016). "Development of arthritis in SKG mice is dependent on IL-17–producing arthritogenic Th17 cells, which are promoted by IL-6 secreted predominately by APCs." (PMID 27288531, 2016). "Interestingly, these cells show an enhanced intrinsic capacity to synthesize the proinflammatory cytokines IL-6 and MMPs ex vivo, suggesting that they could play a pathogenic rather than a protective role in arthritis." (PMID 26980374, 2016). "This treatment yielded a significant improvement of arthritis and physical function in most patients and a decline of acute phase reactants and of resistin, adiponectin, TNF-α, and especially IL-6 levels." (PMID 26526677, 2016). "Ameliorative efficacy of TSE was evaluated on arthritis induced inflammation quantitatively by determining the serum levels of TNF-α, IL-1β, IL-6 and IL-10 using ELISA kits." (PMID 26059174, 2015).
Arthritis (continued). "Proinflammatory cytokines, namely IL-1β, IL-6, IL-17 and TNF act synergistically to maintain inflammation and bone erosions in animal models of arthritis and in RA patients." (PMID 26658436, 2015). "Among the cytokines with the greatest importance in inflammatory responses, pain and arthritis, we selected nine cytokines for further study (IFNγ, TNFα, IL1, IL4, IL6, IL10, IL12, IL17 and IL23)." (PMID 26218592, 2015). "Arthritis severity, serum anti-GPI antibody titers, and IL-6 concentrations were significantly reduced in Padi4 KO mice." (PMID 26293116, 2015). "In the present study, we demonstrated that the severity of arthritis was reduced in GPI-immunized Padi4 KO mice by various changes in immune reactions, including myeloid lineage cells, IL-6, antibodies and Th17 cells." (PMID 26293116, 2015). "In contrast, other pro-inflammatory cytokines such as IL-6, IL-17, transforming growth factor-β, and IL-18 were clearly upregulated in AIA rats and considered to contribute to the pathogenesis of joint inflammation." (PMID 26546348, 2015). "The results revealed that acarbose at the dose of 500 mg/kg/day attenuated the incidence and severity of arthritis and the expression of proinflammatory cytokines, including TNF-α, IL-6 and IL-17 in the paw tissues." (PMID 26678745, 2015). "The experimental results show that both the CsA and the glycyrol treatments reduced the mean arthritis scores, and reduced the contents of IL-1β, TNF-α, IL-6, and IL-17 in the serum." (PMID 25036817, 2014). "In AA model, Mtb induces destructive arthritis through the interaction with immune cells by the abundant release of inflammatory factors (tumor necrosis factor α, INF-γ, interleukin 1, and interleukin 6)." (PMID 25548591, 2014). "TNF-α is produced by macrophages and the synovial lining, and is present at higher concentration in individuals suffering from arthritis; TNF-α modulates the secretion of proinflammatory cytokines (IL-1 and IL-6) within the synovial joints." (PMID 24940448, 2014). "The degree of toe swelling, arthritis index, spleen index, and the expression levels of tumor necrosis factor (TNF)-α, interleukin (IL)-1β and IL-6 were measured." (PMID 25289073, 2014). "Proinflammatory cytokines such as interleukin 6 (IL-6), tumor necrosis factor α (TNF-α) and IL-1β are critical mediators in the inflammatory process of arthritis." (PMID 24886976, 2014). "Asarum extract was found to significantly reduce the severity of arthritis by decreasing hind paw swelling, the arthritis index, the spleen index, and TNF-α, IL-1β and IL-6 expression levels in plasma." (PMID 25289073, 2014). "Cytokine plasma levels of IL-1 beta, IL-6, MIP1 alpha, MCP1, IL-17 and RANTES were increased in arthritis-induced animals." (PMID 23861957, 2013). "IL-1β, IL-6, IL-17, and TNF are found to be elevated during the development of arthritis, and inhibition of TNF and IL-6 represent successful treatments of RA." (PMID 24286140, 2013). "MSCs secrete high levels of IL-6, and it has been demonstrated that IL-6-dependent secretion of PGE2 by MSCs inhibits local inflammation in the mouse model of arthritis." (PMID 24350294, 2013). "GPI-induced arthritis is a newer and closer model of human RA with regard to its dependency on CD4+ T cells and reactivity to biological treatments such as blockade of IL-6 and TNF-α, which are well known to be effective in human RA." (PMID 23251456, 2012). "IL-6 production by NMU-KO macrophages was decreased relative to control macrophages, but IL-6 is dispensable for serum-transferred arthritis." (PMID 22314006, 2012). "We found that IL-6 regulated the expression of SLC19A1, so we also studied the effect of concomitant use of MTX and anti-IL-6 receptor (IL-6R) antibody in this arthritis model." (PMID 22546471, 2012). "Recently, it has been clarified that the development of arthritis in the CIA mouse contributed to the differentiation of IL-17 producing cells (Th17), dependent on IL-6 and TGF-β." (PMID 22577464, 2012).
Arthritis (continued). "In LPS-induced arthritis, mice treated with p38 MAPK inhibitors RO4399247 and AVE8677 diminished IL-6 to background levels." (PMID 22315682, 2012). "Secretion of both IL-6 and TNFα was dose-dependent, with maximal secretion detected at 1 μg/ml of S100A9, a concentration found in the synovial fluid of arthritis patients." (PMID 23029038, 2012). "One study reported that YJB effectively treated arthritis in rats, and our results showing that YJB affects the balance of proinflammatory cytokines IL-6/IL-10 support its anti-CIA activity, further." (PMID 22550538, 2012). "We showed that arthritis was characterized by an early transcriptional activation of the chemokine MCP-1, the proinflammatory cytokines IL-1β, IL-6, and TNFα, and the angiogenic factor VEGF in synovial tissue." (PMID 22414623, 2012). "The MK2 gene deletion protected DBA/1LacJ mice from collagen-induced arthritis due to a significantly lower LPS-induced TNF-α and IL-6 serum levels when compared with wild-type controls." (PMID 22315682, 2012). "In fact, we previously reported that the administration of E-64-d ameliorates the arthritis in CAIA mice via decreased IL-1β and IL-6 production in synovial cells." (PMID 22046434, 2011). "The selected proteins constitute inflammatory mediators and chemokines involved in arthritis, including TNF-α, IL-17, IL-6, MMP-3 and KC." (PMID 20731827, 2010). "In murine AIA, significant and temporal changes in cytokines (IL-1β, TNFα, IFN-γ, IL-6) and factors that govern extracellular matrix turnover (MMP-3, MMP-13, TIMP-1) occur during the acute phase, Days 1 to 3 after arthritis induction." (PMID 20307272, 2010). "Further, baseline IL-6 and ICAM-1 levels significantly correlated with the number of joints with active arthritis at baseline (r = 0.37, p = 0.0059; r = 0.32, p = 0.0096; respectively)." (PMID 20822542, 2010). "Triptolide lowers the arthritic scores, delays the onset of collagen induced arthritis and reduces the expressions of TNF-α, IL-6, NF-κB and COX-2 in paw cartilage in arthritic rats." (PMID 19570240, 2009). "IL-6 and PDGF-BB in D/J.gp130F759 showed distinct kinetics from the other cytokines; higher levels were observed after arthritis development." (PMID 19228423, 2009). "Among the cytokines produced by B cells, IL-6 and IL-10 are of particular interest because of their reported production by CD5+ B cells and their respective pro- and anti-inflammatory effects in arthritis models." (PMID 19706160, 2009). "Increased local levels of IL-1 β, IL-6, TNF-α, MIP-1α, and MIP-2 accompanied the more severe arthritis in IL-4−/− mice." (PMID 19606256, 2009). "To determine the effects of inflammatory cytokines during the effector phase of arthritis, we measured the serum concentrations of TNF-α, IL-6, IL-1β, and IFN-γ at days 0, 7, 14, and 28 in DBA/1 mice after GPI immunization." (PMID 18534002, 2008). "In the present study we demonstrated that treatment with anti-IL-6 mAb inhibited the development of arthritis and even after the onset of arthritis in mice with GPI-induced arthritis." (PMID 18534002, 2008). "A single injection of anti-TNF-α and anti-IL-6 mAbs and two injections of CTLA-4Ig reduced the severity of arthritis in mice, whereas injections of anti-IFN-γ and anti-IL-12 mAbs tended to exacerbate arthritis." (PMID 18534002, 2008). "Our results demonstrate up to 125 fold increases in synovial IL1α and IL1β concentrations, approximately 30 fold increases in levels of IL6 and IL10 and a 200–300 fold elevation in synovial concentrations of TNFα during FCA-induced experimental arthritis." (PMID 17567894, 2007). "It was found that HC could reduce foot swelling in CIA rats, lower the arthritis index, and decrease the secretion of MMP-2, MMP-3, TNF-α, and IL-6." (PMID 41508102, 2026).
Arthritis (continued). "Although this speculation is based on an animal arthritis model study, elevated LRG concentrations in moderate to severe disease itself might promote CRP production via IL-6 and also by T helper 17 cell differentiation." (PMID 39823192, 2025). "The 11 patients with active serositis or arthritis had significantly (P < 0.0001) higher serum IL-6 levels (median 24.21 [3.64–69.26] pg/ml) than those without (median 2.033 [0.6885–6.450] pg/ml)." (PMID 40632603, 2025). "Lactobacillus treatment can prevent the onset of arthritis in preclinical models, reduce arthritis scores in CIA rat and pro-inflammatory cytokines (such as IL-17, IL-1β, IL-6, and TNF-α), and increase the release of anti-inflammatory cytokines like IL-4 and IL-10 in bodily fluids." (PMID 40692793, 2025). "Several studies have demonstrated a correlation between CCR2 and Th17 cells, revealing that mice lacking CCR2 exhibit exacerbated collagen-induced arthritis due to increased Th17 cell activity and elevated levels of IL-17A, IL-6, and IL-1β." (PMID 39903705, 2025). "Inflammation further exacerbates this degeneration, as inflammatory cytokines, such as interleukin‐1 beta (IL‐1β), IL‐6, IL‐18 and tumour necrosis factor‐alpha (TNF‐α), promote ECM degradation, highlighting inflammation as a critical driver of arthritis pathogenesis." (PMID 40179133, 2025). "For instance, in a collagen-induced model of arthritis, treatment with a GSK3 inhibitor reduced joint inflammation and leukocyte infiltration and decreased the production of proinflammatory cytokine such as IL-1β, TNF, IL-6, and IFN-γ." (PMID 39923112, 2025). "Walnut leaf ethanolic extract ameliorated acute inflammation and arthritis in rats by increasing the levels of blood IL‐4, besides attenuating TNF‐α, NF‐κB, IL‐6, IL‐16, COX‐2, and prostaglandin E2 (PGE2) amounts in blood, which resulted in reduced paw edema and arthritic development." (PMID 41179368, 2025). "Apart from the powerful bone-resorbing agents such as TNF-α, IL-1, and IL-6, GGT may also have a role in the pathological expression of RANKL during arthritis." (PMID 40362197, 2025). "It was also not designed to fully analyse the impact of arthritis and serositis on the IL-6–IL-6 receptor system." (PMID 40632603, 2025). "Thus, both cytokines, IL-17 and IL-6, which are critical than TNF-α in arthritis, are inhibited by CRP." (PMID 38650931, 2024). "First, as IL-6 is downstream of IL-1β, systemic inflammation and arthritis were observed in IL-1 but not IL-6 overexpressing transgenic mice in some studies." (PMID 38504360, 2024). "Furthermore, CA treatment has been shown to decrease the expression of proinflammatory cytokines such as IL-1β, IL-6, TNF-α, IL-23, and IL-17 in various arthritis models." (PMID 39684628, 2024). "Moreover, rescue experiments using recombinant IL-6 indicated that the SAA/NFAT5–induced increase in macrophage migration and arthritis progression also is dependent on IL-6." (PMID 38426494, 2024). "This suggests that therapies targeting inflammatory cytokines such as IL-6 and TNF may be fruitful areas of CHIKV arthritis research." (PMID 38507338, 2024). "Cinnamaldehyde can not only significantly reduce the IL-6 content of inflammatory mediator TNF-α in peripheral mononuclear cells of RA patients, but also inhibit the release of IL-1β and matrix MMP-13 from synovial fibroblasts in arthritis patients." (PMID 37033930, 2023). "As TAS5315 ameliorated the arthritis score in an established mouse CIA model, we further measured whether TAS5315 reduced the levels of TNF-α, IL-1β, and IL-6 in synovial fluid exudates derived from the hind paws." (PMID 36821545, 2023).
Arthritis (continued). "Given that elevated levels of IL‐6, IL‐8, and TNF‐α were previously found in CNO cohorts with higher prevalence of arthritis and skin conditions as compared to the present cohort, stratified analysis was performed for these cytokines according to the presence of these additional features." (PMID 38130757, 2023). "Reduction of arthritis scores and spleen and thymus indexes was also observed, as well as the suppression of serum levels of TNF-α, IL-1β, IL-6 and interferon gamma (IFN-γ), which could be attributed to the downregulation of inflammatory mediators." (PMID 37511889, 2023). "Immunohistochemistry of pro-inflammatory cytokine expression in mouse joint tissues showed that the IL-1β, IL-6, and IL-17 levels were significantly decreased in SMILE Tg mice, thus demonstrating the anti-inflammatory effect of SMILE on arthritis in SMILE Tg mice." (PMID 37143079, 2023). "WFR could effectively alleviate the arthritis symptoms of CIA rats; reduce the levels of IL-6, IL-1β, and TNF-α in the peripheral blood of CIA rats; and inhibit the expression of MMP3 and fibronectin." (PMID 38098062, 2023). "The results showed that miR-181a-5p could reduce the release of IL-1β, IL-6, TNF-α and iNOS inflammatory factors in cellular model of arthritis." (PMID 37587519, 2023). "In mouse models of collagen-induced and antigen-induced arthritis, IL-6 inhibition slowed down the progression of arthritis but did not ameliorate arthritis." (PMID 35456929, 2022). "In addition, adjuvants can also induce different immune cells in the knee joint cavity of arthritis to secrete a large number of cytokines (such as TNF-α, IL-1 β and IL-6) and chemokines (including MCP-1, MIP-1α, and RANTES)." (PMID 35572409, 2022). "Clinical arthritis symptoms were reduced, most probably due to quercetin-mediated downregulation of proinflammatory cytokine and chemokine expression (e.g., TNF-α, IFN-γ, MCP1, IL-6, or IL-17)." (PMID 35631330, 2022). "Furthermore, CP-25 alleviated kidney injuries in rats with arthritis through reducing the number of renal CD68+ cells and downregulating the levels of TNF-α and IL-6." (PMID 36457713, 2022). "IL-23 has been recognized as a potent inflammatory cytokine and mediates arthritis progression by promoting the differentiation and maintenance of Th17 cells in conjunction with the release of IL-17, TNF, and IL-6 from Th17 cells, neutrophils, myeloid cells, and RA FLSs." (PMID 36077117, 2022). "Among all genes tested, the expression levels of Cxcl1, Mcp1, Il-1b, and Il-6 were significantly upregulated in the DRG after arthritis remission whereas no significant changes in Tnfα mRNA expression in the DRG were observed." (PMID 35833115, 2022). "Treating the 5-mo-old DNase II−/−STINGS365A/S365A mice with anti–IL-6R reduced the arthritis score and the expression of IL-6 and MMP-3 but did not reduce the expression of TNF-α, CXCL1, and CXCL2." (PMID 34901991, 2022). "We investigated whether the IL-6/STAT3 pathway was inhibited by the synthesized compounds, and then we examined the effect of zymosan-induced arthritis in a rat model." (PMID 35566047, 2022). "IL-6, IL-8, and CD200 play an important role in arthritis and other autoimmune diseases." (PMID 36011369, 2022). "In addition, a high level of IL33 induces the expression of inflammatory cytokines IL1-β, IL6, IL13, and IL17, as well as matrix metalloprotease- (MMP-) 3 and MMP-9 in arthritis." (PMID 34305456, 2021). "LMT-28 could alleviate arthritis and acute pancreatitis in mice, reduce the secretion of TNF-α in serum, and inhibit IL-6-induced phosphorylation of Stat3, gp130 and JAK2 proteins." (PMID 34955842, 2021). "In addition to IL-6, IL-21 and IL-23 can induce STAT3, and both of these compounds take part in arthritis." (PMID 33515210, 2021). "In addition, lower serum levels of TNF-α and IL-6 were also detected in the SPRC group, suggesting that SPRC treatment effectively ameliorated the symptoms and inflammatory responses of arthritis in AIA rats." (PMID 34422677, 2021).